EEF2KMT (eukaryotic elongation factor 2 lysine methyltransferase)
Description:
Catalyzes the trimethylation of eukaryotic elongation factor 2 (EEF2) on 'Lys-525'.
Synonyms: eEF2-KMT; FAM86A; SB153; MGC19636; EFM3
Tractability: Small molecule: a structure with a bound ligand is known. PROTAC: ubiquitination databases record sites on it.
Gene: Protein-coding gene on chromosome 16 (5,084,284 to 5,097,909, reverse strand). Ensembl gene ENSG00000118894.
Subcellular location: Cytoplasm
Subcellular location (Human Protein Atlas): Vesicles
Pathways (Reactome):
Metabolism of proteins: Protein methylation
Gene Ontology:
Molecular function: protein binding; protein-lysine N-methyltransferase activity
Biological process: peptidyl-lysine trimethylation; positive regulation of translational elongation
Cellular component: cytoplasm; protein-containing complex; cytosol
Genetic constraint (gnomAD): Loss-of-function variants: 31 observed, 30.39 expected, observed/expected ratio (o/e) 1.02, 90% interval 0.77 to 1.38. The upper end of that interval is the gene's LOEUF score, 1.38, which puts it in group 5 of 6, group 1 being the genes least tolerant of losing a copy. Missense variants: 495 observed, 416.22 expected, observed/expected ratio (o/e) 1.19, 90% interval 1.1 to 1.28. Synonymous variants: 187 observed, 170.03 expected, observed/expected ratio (o/e) 1.1, 90% interval 0.98 to 1.24.
Homologues: Orthologues: chimpanzee EEF2KMT (98% identical), dog EEF2KMT (79% identical), mouse Eef2kmt (73% identical), rat Eef2kmt (73% identical), tropical clawed frog eef2kmt (52% identical), zebrafish eef2kmt (45% identical), Drosophila melanogaster CG7889 (28% identical), Caenorhabditis elegans R08D7.4 (25% identical). Paralogues in human: FAM86B2 (92% identical), FAM86B1 (83% identical).
Diseases named in the same sentence as EEF2KMT in open-access papers:
EEF2KMT is named in the same sentence as 1 disease in open-access papers, as found by Europe PMC text mining. Sharing a sentence is not in itself a finding about the gene and the disease.
EEF2KMT shares sentences with these, for which no sentence is quoted: cancer (2 papers).